LIPC (lipase C, hepatic type)
Diseases named in the same sentence as LIPC in open-access papers (continued):
Sharing a sentence is not in itself a finding about the gene and the disease.
Hypocholesterolemia (1 paper, 2024). An decreased concentration of cholesterol in the blood. "Interestingly, LIPC gene mutation is the second most common cause of familial hypocholesterolemia, after only angiopoietin-like 3 (ANGPTL3), suggesting that LIPC is a promising target for the diagnosis of familial hypocholesterolemia." (PMID 38195542, 2024).
liver disease (1 paper, 2021). "For example, specific alleles in variants in/near APOE, LIPC, MLXIPL, and TM6SF2 promote liver disease while resulting in a favorable serum lipid profile of decreased TG/LDL or increased HDL, suggesting they may cause liver disease by sequestering lipids/metabolites in the liver." (PMID 33547301, 2021).
lung carcinoma (1 paper, 2023). "The data showed that KLC mice developed lung cancers that migrated from liver tumors, as indicated by high expression of the hepatocyte biomarker lipase C (LIPC) in lung tissues." (PMID 38124228, 2023).
Miscarriage (1 paper, 2015). A pregnancy that ends at a stage in which the fetus is incapable of surviving on its own, defined as the spontaneous loss of a fetus before the 22th week of pregnancy. "The remaining genes assayed had either very low or no expression in cultured chorionic villi from controls (PARK, LIPC, CTNNA3, EGFL6, GPM6B, RAB9A, POU6F2 and C7orf10) and were not assessed in miscarriages." (PMID 25674159, 2015).
myopia (1 paper, 2016). "Furthermore we conducted a meta-analysis of COL8A1, CFI and LIPC genes SNPs (rs669676, rs10033900 and rs10468017) and found that only rs669676 of these SNPs were associated with high myopia neovascularization." (PMID 27643879, 2016).
pulmonary embolism (1 paper, 2022). The obstruction of the pulmonary artery or one of its branches by an embolus, sometimes associated with infarction of the lung. "By comparing the resulting differentially expressed genes with six genes encoding blood metabolites, LIPC and NAT2 were found to be differentially expressed in association with pulmonary embolism." (PMID 36038828, 2022).
Tangier disease (1 paper, 2011). "Mutations in ABCA1 have been associated with Tangier's disease and familial HDL deficiency, and individuals with high HDL-cholesterol levels have homozygous deficiencies of LIPC." (PMID 21858147, 2011).
cardiovascular disease (12 papers, 2010 to 2023). "The information of these clusters indicated the association between SNPs in LIPC with #6 cardiovascular disease and #7 insulin resistance syndrome." (PMID 32341780, 2020). "The association between LIPC polymorphisms and AMD is biologically plausible because this gene is involved with the HDL cholesterol pathway, and cardiovascular disease (CVD) risk factors are associated with AMD." (PMID 21139980, 2010).
tumor (5 papers, 2018 to 2024). "Remarkably, LIPC gene expression correlated with sample type, tumor grade, metastasis status, and HPV status." (PMID 38192945, 2023). "Employing the same set of samples obtained from patient tumors and control samples, our investigation extended to highlight the evident overexpression of LIPC in OSCC tumor samples when juxtaposed with adjacent normal samples (p < 0.05)." (PMID 38192945, 2023). "In our comprehensive analysis, we delved into the expression of the LIPC gene (mRNA) in both tumor and normal samples." (PMID 38192945, 2023). "After checking the expression pattern of LIPC in tumor tissues from HCC patients, the expression level of LIPC mRNA in 30 cases of HCC tissues was lower than that in matched non-cancerous tissues." (PMID 36274132, 2022). "Similarly, the primary tumor weights and liver weights were higher in LIPC overexpressed group, compared with the control group." (PMID 34348759, 2021). "Lipase C hepatic type (LIPC) is a member of the lipase family and plays a role in tumor development." (PMID 38192945, 2023). "This study delves into the relationship between LIPC expression and HNSCC, examining the TCGA-HNSC dataset based on clinicopathological features, prognosis, and tumor infiltration." (PMID 38192945, 2023). "The results illuminated a significant correlation between LIPC gene expression and key clinicopathological features in HNSCC, specifically tumor grade, nodal metastasis status, and HPV status (p < 0.05)." (PMID 38192945, 2023).
cancer (4 papers, 2018 to 2025). A tumor composed of atypical neoplastic, often pleomorphic cells that invade other tissues. "Triglycerides (TRIGL), total cholesterol (CHOL) and lipase C (LIPC)—Lipids are important diagnostic markers, and research has shown that cancer cells induce changes in lipid metabolism." (PMID 40725214, 2025). "LIPC is known to play a role in lipid metabolism, and its dysregulation has been associated with various diseases, including cancer." (PMID 38192945, 2023). "Of particular note was the higher expression of LIPC in HPV-negative HNSCC compared to HPV-positive counterparts, suggesting its potential as a biomarker for the analysis of HPV-associated cancers." (PMID 38192945, 2023). "Given the well-established connection between altered lipid metabolism and cancer, our findings suggested a plausible role for LIPC in the metabolic reprogramming crucial for cancer development." (PMID 38192945, 2023). "Our study identified the overexpression of LIPC in both HNSCC and OSCC tumors, aligning with previous indications of LIPC involvement in various cancer types and its potential as a diagnostic biomarker." (PMID 38192945, 2023). "Based on the Metascape results and other research investigations, we conclude that the LIPC gene is involved in lipid metabolic pathways, which may play a role in cancer development." (PMID 38192945, 2023). "Based on previous studies, LIPC plays a disparate function in different cancers." (PMID 36274132, 2022). "Meanwhile, the aberrant expression of LIPC impacts the onset and progression of cancer, but its role in malignancies has not been concentrated on too much by researchers." (PMID 36274132, 2022).
metabolic disease (2 papers, 2020 to 2022). A congenital disorder (due to inherited enzyme abnormality) or acquired (due to failure of a metabolically important organ) disorder resulting from an abnormal metabolic process. "Importantly, the LIPC gene was more prominently associated with nutritional/metabolic diseases, with the genes GC, HAL and the Cytochrome P450 Family also being implicated." (PMID 36430729, 2022). "Regarding a VD deficiency, the genes LIPC, HAL, GC and the Cytochrome P450 Family genes were among those which are more strongly associated with nutritional/metabolic diseases." (PMID 36430729, 2022). "For instance, the gene LIPC formed a cluster of metabolic diseases." (PMID 36430729, 2022). "The most extensively studied common LIPC variants are located in the promoter, -250G/A (rs2070895) and -514C/T (rs1800588), that have been shown to be associated with HL activity, HDL-C and with the risk of metabolic diseases." (PMID 33326441, 2020).
neurodegenerative disease (1 paper, 2012). A disorder of the central nervous system characterized by gradual and progressive loss of neural tissue and neurologic function. "In the past decade, while a number of case–control studies have been carried out to investigate the relationships between LIPC or CETP polymorphisms and risk of atherosclerosis diseases, little is known about their effect on neurodegenerative disease." (PMID 23181436, 2012).
LIPC also shares sentences with these, for which no sentence is quoted: Insulin resistance (23 papers); hypertriglyceridemia (19); type 2 diabetes (8); hypothyroidism (6); lipid metabolic disorder (4); Hyperglycemia (3); steatosis (3); central obesity (2); chronic kidney disease (2); Hyperinsulinemia (2); Thyroid (2); anemia (1); bladder cancer (1); Borrmann type 4 gastric cancer (1); Brachycephaly (1); cerebrotendinous xanthomatosis (1); Cld (1); cognitive decline (1); colorectal cancer (1); COVID-19 (1); Crohn disease (1); diabetic nephropathy (1); end-stage renal disease (1); familial hyperlipidemia (1); fibrosis (1); geographic atrophy (1); head and neck squamous cell carcinoma (1); hepatic (1); hepatopathy (1); hyperchylomicronemia (1).
A further 17 diseases each share a sentence with LIPC in 1 paper.